STAT3 (signal transducer and activator of transcription 3)
Diseases named in the same sentence as STAT3 in open-access papers (continued):
Sharing a sentence is not in itself a finding about the gene and the disease.
Ewing sarcoma (18 papers, 2009 to 2025). A small round cell tumor that lacks morphologic, immunohistochemical, and electron microscopic evidence of neuroectodermal differentiation. "The KIAA1429-mediated m6A network facilitates Ewing sarcoma cell proliferation and tumorigenesis via the STAT3 pathway and is regulated by NKX2-2." (PMID 37759224, 2023). "In Ewing’s sarcoma, it was found that let-7 directly downregulated signal transducer and activator of transcription 3 (STAT3), consequently reducing the aggressive phenotype." (PMID 35164678, 2022). "In Ewing’s sarcoma, let-7 directly represses signal transducer and activator of transcription 3 (STAT3) and results in a less aggressive cancer phenotype." (PMID 31468250, 2019). "Because phosphorylated STAT3 is frequently upregulated in Ewing sarcoma and PTPRD dephosphorylates STAT3, the role of germline and somatic PTPRD mutations in Ewing sarcoma as well as the implications for IGF-1R targeted therapy warrant exploration." (PMID 23800680, 2013). "One study found that STAT3 activation was present in approximately fifty percent of Ewing sarcoma tissues as assessed by immunostaining." (PMID 19284568, 2009). "For instance, KIAA1429 has been proven to promote the progression of Ewing sarcoma through STAT3." (PMID 40611274, 2025). "Researchers discovered that in Ewing's sarcoma, the presence of let-7 ultimately led to a significant decrease in the levels of signal transducer and activator of transcription 3 (STAT3), which ultimately resulted in a reduction of the cancer's aggressive traits." (PMID 38836981, 2024). "(Of interest, STAT3 phosphorylation is found in about 50% of Ewing's sarcomas)." (PMID 25119929, 2014). "High STAT3 levels have been reported in approximately 50% of patients with Ewing sarcoma, and may be important in tumorigenesis." (PMID 23800680, 2013). "However, the role of germline PTPRD mutations in predisposition to Ewing sarcoma, a disease of children, adolescents, and young adults, and the implications of these mutations for therapy with IGF-1R and STAT3 inhibitors warrants further investigation." (PMID 23800680, 2013). "To examine if STAT3 plays a role in Ewing sarcoma chemoresistance, we depleted endogenous STAT3 in MHH-ES-1 cells and found STAT3 depletion didn’t affect SN-38-induced Akt-pT308 and ERK-p42/p44 (, i)." (PMID 38906855, 2024).
glaucoma (18 papers, 2016 to 2025). Increased pressure in the eyeball due to obstruction of the outflow of aqueous humor. "In astrocytes, overexpression of Stat3 or knockdown of IκKβ/p65, caspase-8, and mitochondrial uncoupling proteins (Ucp2) can reduce ganglion cell loss in glaucoma mouse models." (PMID 36466782, 2022). "Deletion of the STAT3 gene leads to increased RGC loss from experimental glaucoma, as well as reduced astrocyte process expansion." (PMID 32822415, 2020). "Fibroblasts from glaucoma patients with the T104M IL-20RB mutation had higher basal levels of phosphorylated STAT3 compared to wild-type fibroblasts." (PMID 26903709, 2016). "For instance, overexpression of Stat3 or C3, knockdown of IκKβ/p65, caspase 8 and mitochondrial uncoupling proteins (Ucp2) in astrocytes may reduce ganglion cell loss in glaucoma patients in the future." (PMID 36466782, 2022). "This current study reveals a novel mechanism by which baicalin regulates the microglial-ferroptosis interplay through the JAK2/STAT3 pathway in a glaucoma model." (PMID 41208867, 2025). "In glaucoma, we previously showed that attenuation of STAT3-mediated astrocyte reactivity leads to a worse outcome for retinal ganglion cell survival and visual function." (PMID 37759301, 2023). "There was a clear upregulation of inflammatory/immune response genes in the retina detectable at the earliest glaucoma time point, including Gfap, Osmr, Fgf2, Edn2, Stat3, and Socs3." (PMID 37762022, 2023). "Like in the present study, albeit in a different glaucoma model, they also observed an increased STAT3 expression level in the glaucomatous eyes." (PMID 37111243, 2023). "STAT3 plays a core role in the activation of astrocytes in glaucoma and can exhibit neuroprotective or neurotoxic effects on RGCs in different locations and conditions." (PMID 34823561, 2021). "The current study provides novel insights that pro-inflammatory cytokines such as IL-1β and IL-6 are regulated by δ-opioids via STAT3-dependent pathways in rat glaucoma model." (PMID 33628191, 2021). "Moreover, in the injured brain and experimental glaucoma model, conditional knockout of STAT3 from astrocytes attenuated the injury-induced reactive phenotype, pro-inflammatory cytokine activation, GFAP up-regulation, and scar formation." (PMID 37511525, 2023). "Furthermore, beneficial astrocytic behavior is driven by the Stat3 pathway, which can worsen mouse glaucoma damage when genetically removed." (PMID 37762022, 2023). "The astrocytes exhibit increased STAT3 expression in human glaucoma and animal glaucoma models." (PMID 36466782, 2022). "To the best of our knowledge this is the first report in which we have shown that δ-opioid receptor activation regulates phosphorylation of STAT3 at tyrosine 705 which subsequently plays key roles in the regulation of neuroinflammation during glaucoma progression." (PMID 33628191, 2021). "However, Danniel found that knockdown of STAT3 resulted in lower activated astrocytes and a higher apoptosis rate of RGCs in a rat glaucoma model." (PMID 34823561, 2021). "Our results are consistent with previously reported findings, suggesting that specifically targeting STAT3 with miR-93 may effectively break the inflammatory loop and relieve secondary injury in glaucoma." (PMID 33414426, 2021). "In glaucoma patients with the IL-20RB mutation, the IL-20 family of cytokines would not bind efficiently to the IL-20RA/RB receptor so STAT3 would not be activated and translocated to the nucleus." (PMID 26903709, 2016).
glaucoma (continued). "To determine the signaling pathway involved in EPO-mediated phosphorylation of NRF2 in glaucoma, we assessed the ratio of phosphorylated to total PI3K, Akt, JNK, STAT1, STAT3, GSK3β, and MAPK." (PMID 36978804, 2023). "In the WT mice, molecular analysis of the right retina with microbead-induced glaucoma revealed increased expression of the following genes (mean ± SD): BAX 1.44 ± 0.58 fold; TNFα, 1.38 ± 0.32 fold; CD45, 5.45 ± 0.25 fold; STAT3, 2.15 ± 0.72 fold." (PMID 37111243, 2023). "Second, IL-20 stimulation of the mutant IL-20RB leads to abnormal STAT3 activation and MMP activity in glaucoma fibroblasts." (PMID 26903709, 2016). "Blocking the STAT3 signal in the astrocytes exacerbates RGC damage and visual impairment in the glaucoma model, emphasizing the crucial role of reactive astrocytes in protecting RGCs in glaucoma." (PMID 38983026, 2023). "TRPV4 activation induces Müller cell gliosis and TNF-α elevation via the JAK2/STAT3/NF-κB pathway, which may exacerbate RGC apoptosis in glaucoma; these results suggest that TRPV4 can serve as a therapeutic target in glaucoma treatment." (PMID 34789280, 2021). "In addition, TRPV4 activation could enhance the release of inflammatory cytokines (e.g., tumor necrosis factor-α [TNF-α]) through JAK2/STAT3/NF-kB signaling pathways in Müller cells and elevated expression of TNF receptor 1 in RGCs; this process is involved in RGC apoptosis during glaucoma." (PMID 34789280, 2021). "In a rat glaucoma model, but not after optic nerve transection, we found gene expression increases in STAT1 and STAT3." (PMID 32822415, 2020).
HCMV infection (18 papers, 2010 to 2025). "The expression of cmvIL-10, encoded by the UL111A gene, during productive HCMV infection is known to upregulate host IL-10 production in monocytes via phosphatidylinositol 3-kinase (PI3K)/signal transducer and activator of transcription 3 (STAT3) signaling pathway." (PMID 33013921, 2020). "The first five genes are members of the pathways in cancer, among which CASP8, STAT3 and MAPK1 are related to viral carcinogenesis, including Kaposi’s sarcoma-associated herpesvirus and human cytomegalovirus (HCMV) infection." (PMID 40768543, 2025). "Phospho-STAT3 levels were significantly increased in UL26ΔC-infected cells relative to mock or WT HCMV infection." (PMID 38768227, 2024). "The up-regulation of c-Myc, Akt activation, STAT3 activation, and enhanced cyclin-D1 expression are reported in several cell types following HCMV infection." (PMID 30081496, 2018). "These events are followed by diminished STAT3-dependent SOCS3 induction upon hCMV infection or IE1 expression adding to the emerging evidence for transcriptional repression by the viral protein." (PMID 27387064, 2016). "Consistent with previous studies, we show increased levels of STAT3 phosphorylation after HCMV infection." (PMID 25549333, 2014). "HCMV infection induced STAT3 activation in both cell types, whereas incubation of HCMV-infected cells with an IL-6R neutralizing antibody decreased STAT3 phosphorylation." (PMID 23555719, 2013). "HCMV infection induces IL-6 secretion most probably through the expression of the viral-encoded chemokine receptor US28 and the activation of the IL6/STAT3 signaling pathway." (PMID 23592985, 2013). "However, human cytomegalovirus (HCMV) infection inhibits STAT3 phosphorylation but rapidly promotes nuclear localization of unphosphorylated STAT3 to the nucleus and disrupts IL-6-induced gene expression." (PMID 26199948, 2015). "Similarly, in primary human hepatocytes and HepG2 cells the IL-6/STAT3 axis is also activated upon HCMV infection and could favor sustained cellular transformation." (PMID 30081496, 2018). "Although some reports indicate that HCMV infection and/or viral proteins modulate STAT3 intracellular localization, IL-6 signaling, and NF-kB activation, altogether, HCMV participates to shape the tumorous environment and thereby could favor the development and spread of the tumor." (PMID 30081496, 2018). "With the primary human NPC model of HCMV infection, we and others revealed that HCMV infection alters cell fate decisions by intervening with the Notch and STAT3 pathways." (PMID 36753521, 2023). "The HCMV infection of HepG2 and primary human hepatocyte cells results in the activation of the IL-6/JAK/STAT3 pathway, which enhances the HepG2 tumor sphere formation and the transformation of primary human hepatocyte cells." (PMID 32201498, 2018). "Considering the PIAS3 role in inhibition of activated STAT3 pathway and the identified PIAS3 interaction with UL44, there might be a possibility that the STAT3 activity could be enhanced by competitive UL44 binding to PIAS3 during HCMV infection." (PMID 34747321, 2021). "Chronic HCMV infection could potentially promote these important oncogenic signaling pathways since HCMV infection expresses a chemokine receptor US28, which has oncogenic potential and has been shown to signal through the NF-kB pathway and activate downstream COX-2, STAT-3 and IL-6 expression." (PMID 21429243, 2010). "BMX protein expression also increased in response to HCMV infection without IL-6 treatment; therefore, our results identify BMX, a regulator of GBM stemness via STAT3 activation, as a novel target of HCMV." (PMID 25549333, 2014).
lung squamous cell carcinoma (18 papers, 2013 to 2026). "For instance, one study revealed that GOLGA8B can promote lung squamous cell carcinoma by suppressing the expression of STAT3." (PMID 38730195, 2024). "PARD3 contains multiple postsynaptic densities and is localized to tight junctions; in addition, it is correlated with invasion in lung squamous cell carcinoma via impaired STAT3 signaling." (PMID 36213124, 2022). "GOLGA8B knockdown inhibits cell invasion by suppressing the STAT3 signaling pathway in lung squamous cell carcinoma." (PMID 36289596, 2022). "Taken together, these results reveal the importance of PIAS3 as a tumor suppressor of STAT3 activity in squamous cell lung cancer." (PMID 25573684, 2015). "Here, we demonstrate that PTPN13 is a direct transcriptional target of Stat3 in the squamous cell lung carcinoma." (PMID 24191246, 2013). "Importantly, the data also demonstrated the potential activation of STAT3 by a number of upstream receptor tyrosine kinase signaling pathways found to be recurrently amplified in squamous cell lung carcinoma, including PDGFRA and/or KIT, EGFR, and FGFR1." (PMID 25573684, 2015). "ZDHHC19, a key enzyme in the DHHC family, has been reported to be upregulated in human lung squamous cell carcinomas, and high ZDHHC19 expression could promote STAT3 activation through S-Palmitoylation." (PMID 35297315, 2022). "The analogy could also be extended to the lung squamous cell carcinoma subtype and suggests that downregulation of FOXA1 and GATA3 as well as upregulation/activation of EGFR and STAT3 as fundamental components of a generalized basal/squamous-like tumor phenotype." (PMID 26008846, 2015).
Splenomegaly (18 papers, 2010 to 2025). Abnormal increased size of the spleen. "In addition, STAT3 activation due to lysosomal stress likely explains the hyperproliferative kidney disease and splenomegaly observed in AEP-deficient mice." (PMID 30559339, 2018). "Blocking Stat3 activity interferes with the ability of SFFV-P to induce splenomegaly in mice and Epo-independent erythroid colonies in vitro, demonstrating that Stat3 is required for the induction of Epo independence by SFFV." (PMID 21994618, 2010). "In addition to skeletal muscle STAT3 activation, C‐26 tumor‐bearing mice exhibit splenomegaly as a result of increased systemic inflammation." (PMID 31930715, 2020). "To summarize, the combination of HCK overexpression and PTPRT loss was associated with some myeloproliferative characteristics such as hyperproliferation and STAT3 upregulation in vitro, and aberrant bone marrow erythroid maturation, polycythemia and splenomegaly in vivo." (PMID 31065022, 2019). "The disruption of the negative feedback on gp130-dependent STAT signaling causes STAT3 hyperactivation, and these mice develop a broad spectrum of hematopoietic abnormalities, including splenomegaly, lymphadenopathy, thrombocytosis and autoimmune arthritis." (PMID 20059770, 2010). "Within STAT3 GOF syndrome, 73% of patients exhibited lymphoproliferation, primarily presenting as diffuse lymphadenopathy and/or splenomegaly." (PMID 39475099, 2024). "It has previously been reported that hyperactivation of STAT3 results in splenomegaly: here PEGIL11 treatment induced splenomegaly in both wild-type and Asc-/- mice, suggesting IL11-induced splenomegaly occurs via inflammasome-independent mechanisms." (PMID 37292200, 2023). "Young STAT3 GOF mice (<6 weeks of age) had a normal spleen size; however, by adulthood (age 7–16 weeks), significant splenomegaly was observed." (PMID 36136607, 2022). "Overall, these data suggest that STAT3 GOF mice recapitulate many aspects of STAT3 GOF syndrome, including lymphoproliferation with splenomegaly and lymphadenopathy." (PMID 36136607, 2022). "Inhibition of STAT3/5 activity by MCL with a distinct contribution from ruxolitinib, enhances blockage of JAK/STAT signaling in MPNs, thereby improving the therapeutic efficacies of ruxolitinib (including reducing splenomegaly and serum cytokines)." (PMID 37941916, 2023). "Considering the reduction in splenomegaly with these results, the absence of STAT3 in B cells of stat3f/f;CD19Cre/+ mice reduced the total number of viral genome-positive splenocytes by 36-fold, from approximately 286,000 cells in the control mice to 7,910 cells in the stat3f/f;CD19Cre/+ mice." (PMID 27486189, 2016).
diabetic cardiomyopathy (17 papers, 2016 to 2025). Diabetic cardiomyopathy is a disorder of the heart muscle in people with diabetes. "In terms of diabetic cardiomyopathy, punicalagin and paeonol are potent mitochondrial fusion promoters by regulating STAT3 and Opa1 levels." (PMID 39571159, 2024). "In conclusion, increased CCN2 and fibronectin expression levels in parallel with STAT3 activation are identified in diabetic cardiomyopathy." (PMID 28672855, 2017). "Second, according to our findings, it is concluded that the myocardium protective effect of PPARδ in diabetic cardiomyopathy is regulated by STAT3 and we believed that it is indirectly through ROS reduction." (PMID 27519769, 2016). "Previous studies have reported that the combination of BPA and STAT3 may induce diabetic cardiomyopathy." (PMID 41226680, 2025). "The sustained activation of AGE/RAGE-ROS triggers multiple cellular stress-sensitive pathways, such as PKC, NFκB, mitogen-activated protein kinase (MAPK) and signal transducer and activator of transcription 3 (STAT3), amplifying inflammatory and fibrotic responses in diabetic cardiomyopathy." (PMID 40243689, 2025). "Thus, the JAK2/STAT3 pathway may be considered to be of vital importance in ameliorating the effects of OMT against diabetic cardiomyopathy." (PMID 36597092, 2023). "Thus, STAT3 might be considered in future therapies targeting the adverse effects of diabetic cardiomyopathy." (PMID 31709266, 2019).
scoliosis (17 papers, 2012 to 2025). A congenital or acquired spinal deformity characterized by lateral curvature of the spine. "Increases in osteoclast differentiation and functionality have been observed in cases of scoliosis, also associated with the incorrect activation of STAT3." (PMID 35155449, 2021). "Stat3 transcriptional factor, a known promoter of cell proliferation, is associated with human scoliosis, inflammation and cancer." (PMID 28222105, 2017). "Scoliosis, a significant connective tissue anomaly observed in individuals with LDS and those with STAT3-DN mutations, is frequently associated with genetic variations in the ERBIN gene." (PMID 40040707, 2025). "In STAT3-HIES patients, the increased number of osteoclasts has been suggested to cause skeletal symptoms such as scoliosis and pathologic fractures." (PMID 32912316, 2020). "STAT3 regulates the passage of the inflammatory to an anti-inflammatory response and zebrafish mutants show a dysfunction expression of collagen genes during the pathogenesis of scoliosis." (PMID 35155449, 2021). "Patients with autosomal dominant signal transducer and activator of transcription 3 (STAT3) deficiency develop minimal trauma fractures, mostly affecting long bones and ribs; cystic changes of the bones; osteopenia, scoliosis, degenerative spine disease and craniosynostosis." (PMID 33042920, 2020). "Severe scoliosis was reported in two patients with STAT3 defects (2/21) and seven patients without detected genetic defects (7/197)." (PMID 34390440, 2021). "Moreover, non-immunologic findings such as scoliosis, pathologic fractures, characteristic facies, a high arched palate, midline defects, and retained primary teeth have been reported in STAT3-HIES." (PMID 32912316, 2020).